SSU72L1 (SSU72 like 1)
Description:
Protein phosphatase that catalyzes the dephosphorylation of the C-terminal domain of RNA polymerase II. Plays a role in RNA processing and termination.
Synonyms: SSU72P7
Gene: Protein-coding gene on chromosome 11 (4,338,245 to 4,339,345, reverse strand). Ensembl gene ENSG00000284438.
Subcellular location: Nucleus
Gene Ontology:
Molecular function: protein serine/threonine phosphatase activity; RNA polymerase II CTD heptapeptide repeat phosphatase activity; phosphoprotein phosphatase activity
Biological process: termination of RNA polymerase II transcription; mRNA 3'-end processing; mRNA processing; regulation of transcription by RNA polymerase II
Cellular component: mRNA cleavage and polyadenylation specificity factor complex; nucleus
Homologues: Orthologues: tropical clawed frog ssu72 (66% identical), zebrafish ssu72 (66% identical), Drosophila melanogaster Ssu72 (48% identical), Caenorhabditis elegans ssup-72 (46% identical). Paralogues in human: SSU72L4 (99% identical), SSU72L5 (99% identical), SSU72L2 (99% identical), SSU72L3 (97% identical), SSU72L6 (93% identical), SSU72 (71% identical).